AR (androgen receptor)
Diseases named in the same sentence as AR in open-access papers (continued):
Sharing a sentence is not in itself a finding about the gene and the disease.
benign prostatic hyperplasia (continued). "Also, BBR has been reported to suppress the androgen receptor (AR) signaling pathway and prostatic hyperplasia, and has many potential effects on PCOS, although the detailed mechanism remains unclear and there have been no reports on the effect of BBR on ASD development." (PMID 32327976, 2020). "As prostatic hyperplasia develops, its related factors such as PSA and AR are known to be increased." (PMID 30061836, 2018). "However, the role of AR-Vs in the pathophysiology of benign prostatic hyperplasia (BPH) and hormone-responsive PCa needs to be better clarified." (PMID 30028845, 2018). "The pathogeneses of benign prostatic hyperplasia (BPH) and androgenetic alopecia (AGA) are mediated in part by the transcriptional pathways downstream of the steroid hormone androgen receptor (AR)." (PMID 19692448, 2011). "In addition, reduced prostatic hyperplasia and hypertrophy due to the inhibitory effects of GV1001 were exerted via its interaction with AR in the prostate." (PMID 33539321, 2021). "AIM2 activation in response to the cytosolic dsDNA also plays a significant role in benign prostate hyperplasia (BPH) independent of androgen receptor status." (PMID 33643304, 2020). "Therefore, both benign prostate hyperplasia and PCa can be treated pharmacologically by inhibiting the conversion of T to DHT, or by blocking the action of AR." (PMID 31935838, 2020). "We also measured levels of AR, ENO2, and GABBR1 in urine samples from patients with PCa (n = 10) and patients with Benign Prostatic Hyperplasia (BPH) (n = 5)." (PMID 29980692, 2018). "In one fluorescence in situ hybridization (FISH) study, the researchers found AR amplifications to be absent in the benign prostatic hyperplasia (BPH) samples, present in just 2% of the primary PCA tumors, but present in 23.4% of the CRPC tumors." (PMID 35954408, 2022). "Other than humans, dogs are the only other species that develop benign prostatic hyperplasia and sporadic PC; however, male dogs experience a very low incidence of spontaneous PC and are generally androgen independent and lack a functional androgen receptor (AR), unlike PC in humans." (PMID 32674379, 2020). "FISH studies using tissue microarrays showed that AR amplification is present in only 2% of the primary PCa tumor and none of the benign prostatic hyperplasia (BPH) samples, compared to 23.4% of CR-PCa tumors." (PMID 27487144, 2016). "The secretome from activation of stromal-androgen receptor (AR) maintained the basal state of epithelial cells by LGR4/β-Catenin/ΔNP63α signaling and did not induce the clonogenic growth of benign prostate hyperplasia (BPH)." (PMID 35140734, 2021). "However, its action in BPH has not been confirmed, nevertheless the fact AR and ERK are both important in the process of prostatic hyperplasia." (PMID 30061836, 2018).
Obesity (95 papers, 2008 to 2026). Accumulation of substantial excess body fat. "It’s important to note that lifestyle factors (such as obesity, physical inactivity, anabolic steroid use, stress, etc.)can influence hormonal levels, potentially masking the genetic effects of the AR CAG polymorphism in men109." (PMID 41173938, 2025). "Evidence from androgen receptor (AR) knockout mouse models demonstrates that the deficiency of androgen action decreases lipolysis and is mainly responsible for the induction of obesity." (PMID 39124622, 2024). "The androgen receptor (AR) gene can impact fat distribution and body composition, influencing obesity risk." (PMID 38827792, 2024). "In studies of sex hormones, higher androgen receptor density is associated with increased visceral fat, which is more important than total obesity in the carcinogenic role of the liver." (PMID 38418596, 2024). "Disorders of glucose and lipid metabolism in men are associated with age, obesity, and hypogonadism (decreased androgens and/or AR levels) or in male animals with androgen deficiency." (PMID 37900128, 2023). "Consistently, brain-specific deletion of Ar leads to a late onset obesity in male mice, indicating that brain AR is required to prevent aging-associated obesity in males." (PMID 33826123, 2022). "Testosterone signals through the androgen receptor (AR) and AR knockout mice develop obesity, suggesting a functional association between AR and leptin signaling." (PMID 29895265, 2018). "AR is influenced by several growth factors, has known function in growth processes and underlies the obesity phenotype that is commonly found in minipigs." (PMID 30231878, 2018). "Two of the 29 men with an AR mutation (7%) were noted to have obesity with body mass indices of 28 and 30 kg/m2; one had undergone assessment for possible bariatric surgery, and the other had refused any dietetic advice." (PMID 27403927, 2016). "The current study provides clear evidence that deletion of the AR in atherosclerosis-prone apoE-deficient female mice promotes the development of atherosclerosis, as well as obesity and dyslipidemia." (PMID 25550469, 2015). "Androgen signaling in adipose tissue of murine models protects against obesity and regulates insulin action and glucose homeostasis, and AR knockout mice are more susceptible to high-fat diet–induced visceral obesity." (PMID 26445145, 2015). "Similar approaches could be useful for identifying sex-dependent mechanisms linking obesity and OA, including gonadectomy, hormone replacement, and estrogen/androgen receptor genetic mutation and/or agonist treatment." (PMID 39639386, 2024). "In men, experimental studies have shown that AR deficiency worsens obesity and glucose intolerance, suggesting that androgens may play a role in modulating insulin sensitivity in men." (PMID 39765884, 2024). "Obesity-associated OS is proposed to be involved in the conversion of androgen-dependent PCa into androgen-resistant prostate cancer (ARPC) through the regulation of AR expression." (PMID 38068717, 2023). "Therefore, this review aims to describe the current knowledge on the clinical and biological associations between obesity and the AR signaling in BC." (PMID 34066328, 2021). "Thus, in models treated with enzalutamide (anti-androgenic drug), AR inhibition prevented obesity-associated tumor progression by suppressing the proliferation and survival of BC cells." (PMID 34066328, 2021). "Signalling through the androgen receptor (AR) may play a protective role, as disruption of AR predisposes to late-onset obesity, but more so in males than females (when a high-fat diet is required)." (PMID 27647861, 2017). "Adiponectin–resistin (AR) index was proposed as an indicator of metabolic risk in obesity." (PMID 29213336, 2017). "Loss of AR may contribute to an increase of leptin levels and leptin resistance, which may play important roles for the development of obesity and insulin resistance." (PMID 20416077, 2010).
Obesity (continued). "Previous studies in models of obesity and metabolic syndrome have shown that males with reduced testosterone levels also exhibit a decline in AR expression because of a positive feedback loop." (PMID 40036079, 2025). "In summary, the findings so far discussed point each other to the role of androgen/AR pathway impairment in skeletal muscle wasting, sarcopenia progression, obesity, insulin-resistance, inflammation and immuno-senescence." (PMID 40181329, 2025). "Adipose tissue-specific AR knockout mice have increased intra-adipose E2 levels, which leads to pronounced subcutaneous obesity and hyperleptinemia." (PMID 39124622, 2024). "Mechanistic studies have primarily focused on the wild-type AR gene and its involvement in HBV-dependent and obesity-associated hepatocarcinogenesis." (PMID 38182647, 2024). "Nuclear genes, including calpain 10 (CAPN10), cytochrome family P450, insulin (INS) gene, androgen receptor (AR), fat mass obesity (FTO) gene, and follicle-stimulating hormone receptor (FSHR) gene, have been shown to be associated with PCOS." (PMID 37674615, 2023). "Secondly, exercise-related AR activation has been shown to improve blood glucose and lipid levels in male rats with obesity or diabetes by regulating the protein levels of key enzymes involved in glucose and lipid metabolism, such as PEPCK." (PMID 37900128, 2023). "In androgen receptor deficient (ARKO) mice, late-onset obesity and fatty liver, as well as insulin- and leptin-resistance have been reported which is restricted to males." (PMID 35025875, 2022). "While these results suggest potential anti-obesity actions of AR in females, these effects need to be further confirmed in animals with normal apoE functions." (PMID 33826123, 2022). "Further studies examining inflammation with cell-specific knockout of AR and ERs will be critical to decipher the contribution of peripheral tissues and specific immune cells to inflammatory responses in obesity." (PMID 34599964, 2021). "An androgen receptor (AR)-driven oncogene called cell cycle-related kinase (CCRK) cooperates with obesity-induced pro-inflammatory signaling, leading to the development of NASH-related tumorigenesis of the liver." (PMID 34943908, 2021). "In line with this insight, a recent study demonstrated that in a preclinical model of obesity, AR transcriptional activity was increased and promoted ER+ BC progression in environments with low E2 availability (i.e., in postmenopausal cases)." (PMID 34066328, 2021). "The ablation of AR in the pituitary gland resulted in dysregulation of feedback control of glucocorticoid production, which also led to obesity in a mouse model." (PMID 33514065, 2021). "Testosterone plays a critical role in the regulation of body composition in males and exhibits potential anti-obesity effects mediated by the androgen receptor (AR)." (PMID 30002281, 2018). "Mice with a knock-out of the AR suffer a late onset of obesity while being normally sensitive to insulin." (PMID 30231878, 2018). "On the other hand, adipose tissue-specific knock-out of AR resulted in hyperinsulinemia in the absence of obesity, and when fed an HFD, the adipose tissue-specific AR knock-out mice developed obesity, hyperglycemia, and impaired insulin secretion." (PMID 26971100, 2016). "Supporting the notion of the liver as a major target organ, male mice with liver-specific inactivation of the AR [hepatic androgen receptor knockout (H-ARKO)] develop diet-induced obesity, insulin resistance, hepatic steatosis, and dyslipidemia." (PMID 25550469, 2015). "Knockout of AR led not only to development of obesity but also reduction of GPHB5 expression." (PMID 41632528, 2026). "Thus, we studied the impact of early-life or lifelong exposure to a high-fat diet (HFD) on PCa biomarkers [Homeobox B13 (HOXB13) and the Androgen Receptor (AR)] and their correlation with obesity-related markers." (PMID 40481981, 2025).
Obesity (continued). "This circuit acts as a potent upstream activator of mTORC1 signaling in obesity-associated HCC, and is cooperatively induced by obesity-driven pro-inflammatory signals (the IL-6/STAT3 axis) and androgen receptor (AR) signaling—providing a molecular explanation for the male predominance in MASH-HCC." (PMID 41208895, 2025). "A study on AR knockout (ARKO) female mice showed increased body weight, elevated hepatic triglyceride, reduced insulin sensitivity, and higher plasma cholesterol levels, suggesting a protective role of AR against diet-induced obesity and dyslipidemia in females." (PMID 41438090, 2025). "Furthermore, combined WAT, BAT, and brain AR genetic ablation protects against androgen excess-mediated obesity and hepatic steatosis in a mouse model of PCOS." (PMID 38987854, 2024). "Taking all of this into account, AR might be a link between obesity and PCa, making it a useful biomarker for individuals with obesity." (PMID 38068717, 2023). "There are some potential and emerging treatments for SO, for instance, pharmacological interventions (testosterone supplementation, selective androgen receptor modulators, myostatin inhibitors, and anti-obesity drugs), electrical acupuncture and whole-body electromyostimulation, and A2B agonist." (PMID 35371597, 2022). "Interestingly, an androgen receptor (AR)-driven oncogene named cell cycle-related kinase (CCRK) contributes to obesity-induced pro-inflammatory signaling, inducing the development of NASH-related hepatocarcinogenesis." (PMID 36612019, 2022). "Interestingly, all the CT-estimated obesity markers except VAV% were associated with PR and AR positivity; both markers reportedly associated with less aggressive tumors." (PMID 29285243, 2017). "In addition, HFD-dependent obesity is observed in liver-specific AR-KO mice that accumulate triglyceride in the liver and exhibit visceral obesity." (PMID 26961573, 2016). "AR KO mice show late onset of obesity despite ameliorated lipolysis and UCP1 expression." (PMID 24608114, 2014). "In parallel with the AR knockdown db/db mice, in C57BL/6 mice deficient in AR, we found that genetic ablation of AR gene significantly improved MCD diet induced-steatohepatitis in non-obesity and non-diabetic mice." (PMID 24066058, 2013). "In addition, apoE-deficient female mice lacking AR developed diet-induced obesity, dyslipidemia, and atherosclerosis." (PMID 39225098, 2024). "It shouldbe noted that lifestyle factors (obesity, physical inactivity,taking anabolic steroids, stress, etc.)can affect the hormonalbackground, and altered levels of testosterone or estradiolwill mask the genetic effects of the AR CAG polymorphismin men (Wrzoseket al., 2020)." (PMID 38469358, 2024). "The class III obesity (vs. normal/overweight) group was significantly associated with higher expression of CHK1 (log2-fold change = 1.4, p-value = 0.031) and Beclin 1 (log2-fold change = 0.6, p-value = 0.047) but lower expression of androgen receptor (AR; log2-fold-change = −0.8, p-value = 0.039)." (PMID 39766121, 2024). "In addition, it is widely accepted that exercise alleviates or even reverses disorders in glucose and lipid metabolism in individuals with chronic diseases, such as obesity and diabetes, by improving mitochondrial function, which is accompanied by enhanced androgens/AR signaling." (PMID 37900128, 2023). "At present, more compounds of receptors with dual agonists are being tested, for example, GLP-1R/GR (glucagon receptor), GLP-1R/AR (amylin receptor) and GLP-1R/NPYR (peptide YY binds to neuropeptide Y receptors), and might achieve further advances in T2DM, obesity and associated conditions therapy." (PMID 37904255, 2023). "Hence, high AR expression in obesity could play a positive role in BC progression when ER expression levels are low." (PMID 34066328, 2021). "Therefore, the decreased levels of ADPN, observed in obesity and cancer, may favor ER-driven BC progression by reducing the activation of the AR signaling." (PMID 34066328, 2021).
Obesity (continued). "After androgen receptor knockdown in adipocytes in mice, the adipokine levels were altered, and the impaired insulin sensitivity and poor glucose tolerance were found not to be associated with obesity." (PMID 33488512, 2020). "As PMN-MDSCs were also increased in male CCRK TG mice under HFHC diet, our data suggest that the obesity-triggered AR/CCRK signaling may establish an immunosuppressive barrier through induction of MDSC expansion and recruitment via NF-κB/IL-627 and mTORC1/G-CSF42 pathways, respectively." (PMID 30523261, 2018). "In addition, we found a negative association between obesity and the serum AR index value but not with adipose tissue AR." (PMID 29213336, 2017). "There is strong mechanistic overlap between IL-6 signaling, type 2 diabetes, and obesity, particularly through the activation of STAT3 and AR pathways." (PMID 41139205, 2025). "In MASH-related HCC mouse models, the androgen receptor (AR)-driven oncogene, cell cycle-related kinase (CCRK), combined with obesity-induced IL-6/STAT3 signaling, induces lipid metabolic reprogramming and MDSC-dominated immunosuppression." (PMID 38297372, 2024). "The common targets of obesity, T2DM, and AS are estrogen receptor 2 (ESR2), androgen receptor (AR), CYP19A1, NR3C1, SRC, and arachidonate 5-lipoxygenase (ALOX5)." (PMID 39575382, 2024). "It has been reported that andropause, or late-onset hypogonadism, may induce obesity and metabolic syndrome, and testosterone replacement may potentially be an effective treatment for weight management in obese men with hypogonadism possibly mediated via the androgen receptor (AR)." (PMID 35334892, 2022). "Another study reported that an androgen receptor (AR)-driven oncogene, cell cycle-related kinase (CCRK), cooperates with obesity-induced pro-inflammatory signaling to promote NASH-related hepatocarcinogenesis." (PMID 36612019, 2022). "A similar behavior in BC, by decreased levels of ADPN in obesity, would support the inhibitory effect of ADPN in ER− or low ER expression postmenopausal cases, in which AR signaling plays a clearer role as a tumor promoter." (PMID 34066328, 2021). "Male mice with complete (not only hepatic) AR knockout (ARKO) developed increasing triglyceride deposition in liver, obesity, and severe IR." (PMID 32290381, 2020). "More recently, we have also shown that this combination of obesity and OVX-induced overfeeding leads to nuclear localization of the androgen receptor, which promotes the growth of ER+ tumors under conditions of low estrogen availability after OVX." (PMID 29898754, 2018). "Here, we show that an androgen receptor (AR)-driven oncogene, cell cycle-related kinase (CCRK), collaborates with obesity-induced pro-inflammatory signaling to promote non-alcoholic steatohepatitis (NASH)-related hepatocarcinogenesis." (PMID 30523261, 2018). "Mechanistically, obesity-induced pro-inflammatory STAT3 and AR-induced signaling cooperatively up-regulated CCRK expression, which in turn activated the mTORC1 pathway crucial for lipid/glucose homeostasis, immunosuppression, and tumorigenesis." (PMID 30523261, 2018). "For instance, in the context of obesity-driven HCC, the pro-inflammatory cytokine IL-6, in concert with androgen receptor signaling, can induce the expression of the cell cycle-related kinase (CCRK), which in turn establishes a positive feedback loop to drive mTORC1 activation." (PMID 41208895, 2025). "Currently, there are other dual GIPR/GLP-1R agonists available, such as GLP-1R/GR (glucagon receptor), GLP-1R/AR (amylin receptor), and GLP-1R/NPYR (peptide YY binds to neuropeptide Y receptors) and even triple agonists that can activate GIPR to treat obesity and T2DM." (PMID 38987789, 2024). "Active ingredients in WP, such as oxidized glutathione, may improve symptoms of HFD-induced obesity by acting on targets such as EGFR, NOS3, MMP2, PLG, PTGS2, and AR." (PMID 38162665, 2023).